CRP (C-reactive protein)
Diseases named in the same sentence as CRP in open-access papers (continued):
Sharing a sentence is not in itself a finding about the gene and the disease.
co-infection (continued). "RMPP children who had co-infection with other pathogen had a longer process of fever, higher leukocyte count, higher C-reactive protein and a higher incidence of pneumothorax or diffuse large area of inflammation in the lung." (PMID 29970200, 2018). "The ESR and CRP had a moderate effect on the identification of co-infection with HIV and either TB or NTM." (PMID 29092717, 2017). "pneumoniae positive PCR and a concentration of CRP equal or higher than 20 mg/l; viral RNA/DNA was additionally detected, indicating a possible bacterial co-infection." (PMID 29149199, 2017). "A plausible explanation for similar CRP levels in both groups of patients is the possibility of concurrent bacterial co-infection, as other investigators have noted higher CRP values in this setting." (PMID 23418448, 2013). "Furthermore, these CRP levels were significantly elevated compared to the mean measured CRP levels in patients with viral mono-infection, virus-viral co-infection, and bacterial-viral co-infection (p < 0.05)." (PMID 41210881, 2025). "In addition, a fivefold increase in measured mean CRP levels was documented in patients with monobacterial co-infections." (PMID 41210881, 2025). "Furthermore, in all combinations of mono- and co-infections, we observed a three- to six-fold increase in CRP levels, exceeding the normal threshold of <5 mg/L." (PMID 41210881, 2025). "Moreover, hospitalized patients aged >65 with viral-viral co-infections exhibited significantly higher C-reactive protein levels (150.8 ± 14.3 mg/L) compared to children aged < 15 (p < 0.05)." (PMID 41210881, 2025). "Increased WBC and CRP indicated an infection status due to possible bacterial co‐infection." (PMID 41144944, 2025). "Significant changes in prealbumin and CRP were observed in coinfected patients, and these indicators could serve as valuable tools for the early identification of co‐infection alongside epidemiology and common symptoms." (PMID 38270315, 2024). "CRP and prealbumin serve as an early warning of co‐infection, which can help healthcare workers assess whether co‐infection is present, and alert healthcare workers to perform nucleic acid testing to identify the pathogens and adjust treatment strategy timely." (PMID 38270315, 2024). "HSV coinfection was associated with highest WBC count, CRP, ESR, and BUN." (PMID 39014398, 2024). "Nevertheless, other studies have demonstrated that rhinovirus monoinfections may be associated with mild to moderate elevations in serum CRP values, and that very high increases in CRP may indicate the possibility of a bacterial co-infection or superinfection." (PMID 39594877, 2024). "Elevated CRP and ALT levels are linked to increased co-infection likelihood." (PMID 38793006, 2024). "In bacterial-Aspergillus co-infection, serum levels of CRP and PCT may be higher in patients than in Aspergillus infection alone." (PMID 38633749, 2024). "CRP may have been a more informative outcome measure if a higher rate of co-infection had been found." (PMID 39506794, 2024). "In addition, co-infection with a virus and high CRP value also increased the odds ratio for MRSA infection." (PMID 39483528, 2024). "However, CRP and ferritin remained significantly higher in those with co-infections despite similar and high rates of virologic suppression in both groups." (PMID 38725704, 2024). "Higher C-reactive protein levels and the higher frequency of fever seen in children with viral coinfections from our cohort could reflect this more intense inflammatory response." (PMID 37845714, 2023). "Of the 187 cases who had peripheral blood C‐reactive protein (CRP) tested, 178 (95.2%) had CRP < 8 mg/L, 8 (4.3%) had CRP > 8 mg/L (range: 8.8–35.8 mg/L), and 1 (0.5%) had CRP 56 mg/L who had co‐infection with M. pneumoniae and developed typical lobar pneumonia in the right lung." (PMID 36043446, 2022).
co-infection (continued). "Furthermore, median biomarkers of inflammation (ALT, AST, and CRP) were significantly lower in patients with SARS-CoV-2 + rhinovirus co-infection in comparison to patients with SARS-CoV-2 mono-infection." (PMID 36612967, 2022). "In this study, co-infections were associated with a higher CRP and presenting heart rate but not other significant markers of severe illness i.e. longer duration of hospitalisation, need for NIV, PICU care, oxygen therapy and nasogastric tube feeding." (PMID 32059033, 2020). "Co-infection was associated with a higher CRP and heart rate but not with other parameters of severe infection." (PMID 32059033, 2020). "C-reactive protein level was elevated only in children with bacterial co-infection or KD." (PMID 32674306, 2020). "Similarly, Shin et al10 reported that serum CRP levels were significantly higher in patients with bacterial co‐infection compared with those infected with H1N1 alone." (PMID 30443990, 2019). "Univariate analysis revealed significant associations of serum PCT, CRP, and WBC levels with co‐infections with H1N1 and bacteria (odds ratio [OR]: 1.65, 95% confidence interval [CI], 1.34‐2.06, P < 0.001; OR: 1.08, 95% CI, 1.06‐1.09, P < 0.001; OR:1.06, 95% CI, 1.04‐1.09, P = 0.02, respectively)." (PMID 30443990, 2019). "The combination of PCT and CRP levels could provide a useful method of distinguishing bacterial co‐infections from an H1N1 influenza infection alone in children during the early disease phase." (PMID 30443990, 2019). "The analysis revealed that HIV-helminth coinfection was associated with patterns of lower prealbumin and albumin levels across all BMI categories in the subgroup with normal CRP except in the obese, although not statistically significant." (PMID 30065944, 2018). "However, in this age group, bacterial mono-infections (mean CRP 66.6 ± 80.6 mg/L) and one reported viral co-infection (CRP 52.3 mg/L), as well as mixed bacterial-viral co-infections (mean CRP 58.4 ± 70.2 mg/L), demonstrated approximately five- to six-fold CRP increase." (PMID 41210881, 2025). "However, co-infection may result in elevated white blood cell and neutrophil counts, along with increased inflammatory markers, such as erythrocyte sedimentation rate and C-reactive protein." (PMID 40108488, 2025). "Therefore, one could say that lower CRP levels may be produced, in reality, due to bacterial co-infection." (PMID 37873776, 2023). "Specifically, patients with co-infection of C. psittaci and C. abortus had the highest peripheral blood CRP levels compared to other Chlamydia infection subgroups, indicating that co-infection might lead to severer pulmonary infections and a pan-systemic inflammatory state." (PMID 37434780, 2023). "CRP may be an effective biomarker to assess bacterial co-infection in HFRS." (PMID 35677912, 2022). "Results showed that serum ferritin and PCT concentrations have a robust association with severity and mortality of HFRS, which can be used as promising predictors of severity and mortality, and CRP may be an effective biomarker to assess bacterial co-infection in HFRS." (PMID 35677912, 2022). "However, high CRP levels were associated with marked heterogeneity in PCT, and the highest PCT levels may also reflect genuine bacterial co-infection, which might be underestimated by the diagnostic limits of microbiological testing." (PMID 34859223, 2021). "Thus, MPV might be used as a potential indicator to evaluate whether TB or DM will develop into TB-DM coinfection, and it is correlated to the inflammatory index (CRP and ESR)." (PMID 34016046, 2021). "WCC and CRP have limited discriminatory capacity, and PCT has been increasingly used to provide more diagnostic certainty, with several studies using low PCT values, which support the exclusion of bacterial co-infections, to safely reduce antibiotic prescribing." (PMID 34859223, 2021).
co-infection (continued). "Finally, liver dysfunction and immunomodulators (e.g. dexamethasone or tocilizumab) may limit CRP elevations in some bacterial co-infections." (PMID 34859223, 2021). "Co-infection was associated with a higher CRP but no other parameters of severe clinical illness." (PMID 32059033, 2020). "Furthermore, the combination of PCT and CRP levels could represent a useful method for screening bacterial co‐infections from H1N1 influenza infections alone in children during the early disease phase." (PMID 30443990, 2019). "Finally, we analysed whether bacterial co-infection can be predicted using clinical or laboratory markers such as C-Reactive Protein (CRP)." (PMID 31694565, 2019). "Thus, in the present study, we conducted a retrospective analysis of 3180 children with H1N1 infection to evaluate the diagnostic levels of serum PCT, CRP and WBC alone and in combination for differentiating bacterial co‐infections from H1N1 influenza infections alone in children." (PMID 30443990, 2019). "The baseline lipid profile, CD4+ cell count, platelets, CRP, PCT, TNF-α, VCAM-1, and HCV and HBV coinfection were evaluated." (PMID 40006998, 2025). "Consider use of biomarkers (e.g., FBC, CRP, PCT) and blood cultures for diagnosis of serious bacterial co‐infection for infants being admitted to ICU with bronchiolitis." (PMID 40685806, 2025). "We considered the top 20 including: Urea (abnormal), Age, PT (abnormal), CRP (abnormal), NLR (Severe), APPT (moderate), PLT (mild, moderate), Neutrophils (mild, severe), Lymphocytes (severe), blood co-infection, hemoglobin (severe), blood pH (abnormal)." (PMID 40065374, 2025). "This study therefore aimed to assess virological outcomes, iron, ferritin and CRP levels among PLWH and co-infections, after initiating a dolutegravir-based ART." (PMID 38725704, 2024). "In this study, we assessed changes in HIV VL, iron, ferritin, and CRP among PLWH and co-infections following 6-month initiation on a dolutegravir-based ART." (PMID 38725704, 2024). "From this, the variables of Coefficient > 0 are MP, co-infection, co-infection virus, LOS, FDP, B cell, GLB, WBC, NEUT, APTT, Pulse, LDH, ALT, CRP, CK, CKMB and D-dimer." (PMID 39385312, 2024). "In a large observational study of 4635 patients from 84 ICUs, neither PCT nor CRP were independently associated with bacterial co-infection, but baseline values of PCT < 0.3 ng/mL could be useful to rule out bacterial pneumonia (negative predictive value of 91.1%)." (PMID 37510807, 2023). "In this study, RA and SLE patients with co-infection with HBV had significantly higher ESR and CRP levels than the normal population." (PMID 37680831, 2023). "The severity of inflammation (WBC, N, ESR, CRP), inflammatory anemia, and prevalence of involved sites in TM and NTM co-infection were more evident than in TM or NTM mono-infection, especially when compared." (PMID 34376749, 2021). "C-reactive protein (CRP) (P = 0.02) and the aspartate aminotransferase (AST) (P = 0.04) in EBV/SARS-CoV-2 coinfection patients were higher than that in SARS-CoV-2 infection alone patients." (PMID 34035353, 2021). "The levels of AIGAs, WBC, N, ESR, and CRP in TM and NTM co-infections were remarkably higher than in mono-infection." (PMID 34376749, 2021). "The patients with co-infection had higher median PCT (4.35 [IQR 0.6–19.5] versus 0.6 [IQR 0.2–2.3] ng/mL, p = 0.001) and CRP levels (36.7 [IQR 20.23–118] versus 28.05 [IQR 13.3–109] mg/dL, p = 0.001]) when compared with PVP." (PMID 33810263, 2021). "The PCT&CRP was superior to use of the PCT, CRP and WBC alone in differentiating patients with bacterial co‐infections from those infected with H1N1 alone." (PMID 30443990, 2019). "The performance of the ROC curves of the constructed model, PCT, CRP, and WBC levels for differentiating children with H1N1 and bacterial co‐infections from children infected with H1N1 alone was compared." (PMID 30443990, 2019).
co-infection (continued). "Host-protein signature, CRP, IL-6, and PCT mean levels in mixed infections (bacterial and viral co-infection) are comparable to those found in pure bacterial infections (p > 0.14)." (PMID 29700762, 2018). "According to the review, models were unlikely to include a broad range of variables concerning co-infection, biochemical factors (outside of C-reactive protein), and other haematological factors on an individual patient level." (PMID 40065374, 2025). "Median C-reactive protein (CRP) and procalcitonin (PCT) levels were significantly higher in patients with Influenza B compared with those with Influenza A or Influenza A + RSV co-infection (p = 0.048 and p = 0.023, respectively), suggesting a more pronounced systemic inflammatory response." (PMID 41597022, 2025). "Compared to the non-severe group, more frequent underlying condition, wheezing, and seizures, as well as higher fever peak were observed in the severe group, with higher levels of leukocyte count, NLR, CRP, PCT, IL-6, IL-10, D-dimer, and more frequent co-infection (all P < 0.05)." (PMID 39114651, 2024). "We found that participants with co-infections had significantly higher CRP and ferritin, but lower iron levels than those without co-infections at baseline." (PMID 38725704, 2024). "Moreover, significant differences were observed in the incidence of AMH, co-infection rates, peripheral white blood cell (WBC) count, and C-reactive protein levels." (PMID 39483762, 2024). "CRP levels were 26.1 ± 11.1 mg/dL in the co-infection group and 10.0 ± 10.1 mg/dL in the group without co-infections (p < 0.001)." (PMID 37326938, 2024). "Prior to ART initiation, participants with co-infections had higher VL, CRP and ferritin, and lower iron levels, compared to those without co-infections (P < 0.001)." (PMID 38725704, 2024). "Following 6 months of ART, CRP and ferritin levels decreased while iron levels increased, regardless of co-infection status." (PMID 38725704, 2024). "Meanwhile, many inflammatory factors were increased in EBV coinfection groups: CRP was highest in EBV/fungi coinfection, while PCT and IL-6 were increased significantly in EBV/bacteria coinfection, indicating more complicated syndromes in EBV coinfections." (PMID 37026057, 2023). "In contrast, the statistical test evaluated that among the co-infected group, CRP and D-dimer were significantly higher compared to those without co-infection." (PMID 37630481, 2023). "White blood count, C-reactive protein and procalcitonin, having a specificity of over 82% and a low sensitivity under 40%, can predict the absence of a bacterial co-infection." (PMID 36671351, 2023). "The CRP level in HFRS with bacterial co-infection (n = 115) was higher than that without bacterial co-infection (n = 258, p < 0.001)." (PMID 35677912, 2022). "A large prospective, multicenter study of patients with influenza A (H1NI) showed that PCT < 0.29 ng/mL had a 94% negative predictive value for excluding bacterial co-infection and was superior to CRP." (PMID 35775463, 2022). "BV outperformed routine biomarkers, including CRP, correctly identifying children with adenoviral infections (without bacterial co-infection) even when inflammatory markers were high." (PMID 36389361, 2022). "In non-bacterial inflammations, PCT is either in normal range or slightly elevated, which makes it a more desirable biomarker rather than CRP to predict bacterial co-infection." (PMID 35246169, 2022). "Patients with confirmed co-infections had higher levels and more spikes of CRP and PCT than patients without." (PMID 35420370, 2022). "Interestingly, in patients with TBE, CRP, WBC, and the percentage of neutrophils in peripheral blood were higher than in patients with TBE co-infection." (PMID 35456059, 2022). "Procalcitonin and CRP in patients with bacterial co-infection were significantly higher than those in patients with non-bacterial co-infection (both p < 0.001)." (PMID 35677912, 2022).
co-infection (continued). "In 124 (53%) patients CRP was below 100 mg/L, chest CT was not consistent with co-infection and microbiological test results were negative." (PMID 34717761, 2021). "In this study, patients with co- infection had a higher CRP and initial heart rate but no other markers of clinical severity like longer duration of hospitalisation and need for increased respiratory or medical support." (PMID 32059033, 2020). "The mean CRP value in the single RMPP patients showed no statistical differences compared with that of the RMPP patients with co-infection (103.5 ± 66.86 vs. 19.33 ± 87.38, t = −0.258, P > 0.05)." (PMID 33194797, 2020). "The CRP concentration and the poor prognosis rate in the single M. pneumoniae infection RMPP patients both showed no statistical differences compared with that of the RMPP patients with co-infection." (PMID 33194797, 2020). "Another drawback was that only one study investigated co-infection (viral-bacterial) and concluded that CRP level did not correlate with co-infection." (PMID 31918745, 2020). "In clinic CRP levels higher than 40 mg/L (sometimes higher than 160 mg/L, normal range < 8 mg/L) would prompt clinicians to consider potential bacterial co-infection and prescribe both non-anti-MP and anti-MP antibiotics to RMPP patients." (PMID 30416990, 2018). "Our studies suggested that bacterial co-infection in the early stage of pediatric RMPP patients was low and CRP level might be mainly a marker of inflammation." (PMID 30416990, 2018). "Secondly, all patients whose CRP were higher than 100 mg/L with NGS results received Group A or B non-anti-MP antibiotics only for 2–3 days, which were promptly discontinued once NGS result didn't reveal any bacterial co-infection." (PMID 30416990, 2018). "While a co-infection cannot be ruled out when both MxA and CRP are elevated, this condition was not seen in the current clinical trial." (PMID 28991170, 2017). "In three patients presenting co-infection with coagulase-negative staphylococcus, we found a CRP higher than 20 mg/l, and in one patient presenting septic infection involving both hip prostheses a CRP of 110 mg/l." (PMID 27017334, 2016). "In this study the immune and C-reactive protein (CRP), haptoglobin (Hp), serum amyloid A (SAA) or/and pig major acute phase protein (Pig-MAP) responses after simultaneous co-infection with common porcine pathogens: SIV (H1N1 subtype) and Pm were evaluated in piglets." (PMID 23332090, 2013). "Our study shows that high ferritin levels are strongly (and inversely) related to CD4 cell numbers but not to gender, HCV co-infection nor CRP as a marker of inflammation, as has been suggested by others." (PMID 21827653, 2011). "The median CRP levels among all patients in our cohort (113 mg/L; no bacterial co-infection) align with those previously reported in febrile patients with confirmed fungaemia (mean 113 ± 69 mg/L), thereby supporting its potential role as an inflammatory marker in this setting." (PMID 41003190, 2025). "Prealbumin and C‐reactive protein (CRP) levels were analyzed in 161 COVID‐19 cases infected by SARS‐CoV‐2 (wild type), 299 cases infected by Omicron, 95 cases infected by influenza virus A/B (Flu A/B) and 133 co‐infection cases infected with Flu A/B and Omicron." (PMID 38270315, 2024). "Similarly, plasma levels of CRP and ferritin were significantly higher in participants with co-infections than those without." (PMID 38725704, 2024). "Thus, CRP genotype might play a significant role in determining serum-CRP concentration, viral load, and dengue-CHIKV mono/co-infection." (PMID 37703107, 2023). "CRP and WBC are not highly specific in differentiation between viral and bacterial infections and better biomarkers or microbiologic methods would be needed in order to confirm or exclude bacterial co-infection in RV-associated CAP." (PMID 31750306, 2019).